PARP1 (poly(ADP-ribose) polymerase 1)
Diseases named in the same sentence as PARP1 in open-access papers (continued):
Sharing a sentence is not in itself a finding about the gene and the disease.
cardiovascular diseases (21 papers, 2009 to 2025). "A series of in vivo studies from the Boulares and Matter groups used PARP1-deficient mice to demonstrate that PARP1 promotes the development of various cardiovascular disorders." (PMID 32029454, 2020). "Poly (ADP-Ribose) Polymerase 1 (PARP1) is an important damaging factor in cardiovascular disease, especially cardiac remodeling caused by various factors 77-79." (PMID 33110392, 2020). "Parthanatos is a caspase-independent PARP-1 hyperactivation-mediated cell-death pathway involved in various pathophysiological processes, including neurological and cardiovascular diseases." (PMID 39940397, 2025). "PARP1 is considered as a potential target for cardiovascular diseases, especially pathological cardiac hypertrophy." (PMID 35002525, 2022). "Their results indicated that PARP1 inhibition can be a therapeutic target for the treatment of cardiovascular diseases." (PMID 34124031, 2021). "Recently, several studies have also shown that PARP1 participates in oxidative stress-related cardiovascular diseases, including ischemia reperfusion injury." (PMID 31178959, 2019). "The utilization of PARP1 as a therapeutic target for related cardiovascular diseases would be desirable." (PMID 30323296, 2018). "Growing evidence reveals that poly(ADP-ribose) polymerase-1 (PARP1) is involved in the progression of many cardiovascular diseases." (PMID 30323296, 2018). "A previous investigation found that PARP-1 is important in a variety of cardiovascular disease processes and that the catalytic activity of PARP-1 increases significantly in the development of these diseases." (PMID 25872931, 2015). "PARP-1 plays a crucial role in the progression of various cardiovascular diseases." (PMID 37831380, 2024). "On the other hand, the partial inactivation of PARP-1 by fragmentation could be beneficial for the Sm venous cell population, as increased activation of PARP-1 may contribute to the pathogenesis of various cardiovascular diseases." (PMID 38612704, 2024). "In recent years, PARP-1 has been extensively studied in cardiovascular diseases." (PMID 32139662, 2020). "PARP1 is widely involved in oxidative stress-related cardiovascular diseases." (PMID 31178959, 2019). "Thus, the findings from the current study contribute to a further appreciation of the importance of PARP1 activation in cardiovascular diseases." (PMID 30898999, 2019). "Additionally, hyper-activation of PARP1 promotes the expression of pro-inflammatory genes, which can aggravate various cardiovascular diseases, such as myocardial infarction and coronary artery disease." (PMID 26522181, 2015). "Additionally, perhaps preventing PARP1 transport into mitochondria via inhibition of the Mitofilin/PARP1 interaction could overcome certain PARP1 side-effects in treatment of cardiovascular disorders." (PMID 33482196, 2021). "Previous studies have demonstrated that poly(ADP-ribose) polymerase-1 (PARP1) participates in the progression of various cardiovascular diseases, and various reports have proved that PARP1 can be a therapeutic target in these diseases, but whether it plays a role in MIRI is still unknown." (PMID 34124031, 2021). "Hence, PARP1 plays an important role in regulating cardiovascular diseases." (PMID 31178959, 2019). "Moreover, PARP activation, especially of PARP1, was previously found to be involved in various cardiovascular diseases other than AF11,12,15–17, and both pharmacological and genetic inhibition of PARP1 provides significant benefits in animal models of such cardiovascular disorders." (PMID 30898999, 2019). "The present study confirmed that the PARP1 inhibitor, ABT-888, inhibited the effect of high concentrations of aldosterone on the injury of cultured endothelial cells, suggesting a novel direction in the treatment of cardiovascular diseases caused by aldosterone." (PMID 25872931, 2015).
cardiovascular diseases (continued). "However, the exact mechanism by which PARP-1 mediates development of these diseases needs to be better clarified in order for PARP-1 inhibition to be a potential target as a viable therapeutic strategy for cardiovascular disorders." (PMID 19823587, 2009). "In this article, we review the current understanding of DNA damage-PARP1-NAD+ axis in the pathogenesis of AF and cardiovascular diseases." (PMID 32411727, 2020). "In cardiovascular diseases, PARPi, such as 3-AB, PJ-34, INO-1001, BGP-15, and GPI 6150, reduce the consumption of NAD+ and ATP by inhibiting the overactivation of PARP1, thereby alleviating oxidative stress and inflammatory responses and protecting cells from necrosis." (PMID 41460301, 2025).
metabolic disorders (15 papers, 2013 to 2026). "Various research has linked PARP1 with the aging associated metabolic diseases as well as brain diseases." (PMID 33805567, 2021). "Human-PARP1 overexpressed mice had prolonged disease-free survival, reduced tumor burden, but were more susceptible to aging related metabolic disorders." (PMID 33805567, 2021). "Deletion or pharmacological inhibition of PARP1 supports mitochondrial biogenesis and function, providing protection against metabolic disease." (PMID 35734882, 2022). "PARP1 knockout mice exhibited an increase in mitochondrial content and energy expenditure and were protected against metabolic disease confirming that PARP1 influences SIRT1 activity in maintaining mitochondrial homeostasis." (PMID 34178728, 2021). "In such conditions, overactivated mitochondrial PARP1 depletes NAD+, causing metabolic disorder and cell death." (PMID 33482196, 2021). "Enrichment analysis revealed NAD+-related metabolic disorders induced by excessive activation of PARP1 after DNA damage." (PMID 33425964, 2020). "When phosphorus metabolism disorders occur, activated PARP1 promotes vascular calcification." (PMID 30867423, 2019). "Intramitochondrial PARP1 resulted in NAD+ depletion and lead to metabolic disorder, reduced ATP production, and cell death." (PMID 33482196, 2021).
prostate (13 papers, 2015 to 2025). "Two-sample Mendelian randomization analysis results showed a significant causal relationship between elevated PARP1 levels and reduced risk of Undescended Testis." (PMID 40937411, 2025). "In this study, we further confirm that PARP-1 activates the NF-κB pathway in macrophages, leading to prostatitis." (PMID 40032778, 2025). "Our results reveal that PARP1 aggravated prostatitis, and promoted macrophage and neutrophil infiltration at inflammatory sites and upregulates the expression of inflammatory cytokines such as IL-6, CCL2, and TNF." (PMID 40032778, 2025). "Subsequently, we further explored which of macrophages or neutrophils played a more crucial role in the PARP1-regulated prostatitis model." (PMID 40032778, 2025). "Taken together, these findings demonstrate that PARP1 regulates neutrophils and macrophages recruitment in prostatitis." (PMID 40032778, 2025). "Collectively, these findings indicated that PARP1 plays a crucial role in regulating inflammatory mediators level at the site of inflammation in a validated model of prostatitis." (PMID 40032778, 2025). "Previous studies have shown that the inhibition of PARP1 in HepG2 cells transfected in nude mice prevented liver cancer." (PMID 30271949, 2018). "Collectively, our study provides a theoretical basis for new applications of PARP1 inhibitor, which could be a possible new option for the treatment of prostatitis." (PMID 40032778, 2025). "In conclusion, we discovered that PARP1 could exacerbate prostatitis by facilitating macrophage infiltration and differentiation to the M1 phenotype." (PMID 40032778, 2025). "This study probed into the regulatory role of PARP-1 in prostatitis." (PMID 40032778, 2025). "Consequently, the findings indicated that PARP1 was capable of positively regulating the progression of prostatitis." (PMID 40032778, 2025). "PARP1 is recognized for its role as a DNA damage sensor and its involvement in inflammatory diseases, but its impact on prostatitis remains unclear." (PMID 40032778, 2025). "Therefore, this study utilized a carrageenan-induced prostatitis model to investigate the impact and potential mechanism of PARP1 on the onset and progression of prostatitis." (PMID 40032778, 2025). "We aimed to elucidate how PARP1 affects prostatitis progression." (PMID 40032778, 2025). "The main potential mechanism by which PARP1 might regulate the secretion of inflammatory factors in M1-like macrophages through NF-κB signaling to alleviate carrageenan-induced prostatitis." (PMID 40032778, 2025). "The results of macrophages (CD45+CD11b+F4/80+) density in the prostate tissue revealed that prostatitis induced by 1% carrageenan increased the percentage of macrophages in WT model group, and also increased in Parp1−/− model mice when compared with corresponding control mice." (PMID 40032778, 2025). "Conversely, inhibiting or knocking down PARP-1 activity in macrophages alleviates prostatitis." (PMID 40032778, 2025). "However, the ratio of macrophages significantly in the Parp1−/− model group was significantly lower than that in the WT model group, suggesting that PARP1 knockout suppressed the recruitment of macrophages in prostatitis." (PMID 40032778, 2025). "CXCL1 levels in the plasma, however, remained unchanged upon inhibition of PARP-1 after liver IR." (PMID 29179487, 2017). "Notably, the prostate lesions in the Parp-1−/− model group were significantly milder than those in the WT model group, suggesting that PARP1 might play a role in regulating the process of prostate inflammation." (PMID 40032778, 2025). "Additionally, the expression of IL-6, IL-12p70, CCL2 and TNF in the Parp1−/− model group was markedly reduced and IL-10 increased significantly compared to that in the WT model group, suggesting that PARP1 enhanced the inflammatory factors secretion in prostatitis." (PMID 40032778, 2025). "However, the precise role of PARP1 in the prostatitis remains unclear." (PMID 40032778, 2025).
prostate (continued). "Collectively, these findings indicated that PARP1 exacerbates carrageenan-induced prostatitis by promoting M1 macrophages polarization via the NF-κB pathway, suggesting PARP1 could be a potential therapeutic target for macrophage-based treatments in prostatitis." (PMID 40032778, 2025). "Mechanistically, PARP1 promote the NF-κB expression, which could regulate downstream inflammatory cytokines, including IL-6, IL-10, IL-12p70, CCL2, IFN-γ in M1 macrophages, leading to the accumulation of proinflammation factors and ultimately exacerbating prostatitis." (PMID 40032778, 2025).
adenocarcinoma (10 papers, 2008 to 2024). A common cancer characterized by the presence of malignant glandular cells. "PARP-1-positive cells resulted higher in the normal pancreas compared with the pancreas with adenocarcinoma." (PMID 32850156, 2020). "The increased expression of poly (ADP-ribose) polymerase 1 (PARP1) was linked to a Cyanobacteria presence in the lung, and the PARP1 expression was significantly increased in the adenocarcinoma lesion infected with Cyanobacteria compared to neighboring non-cancerous tissues." (PMID 37894302, 2023). "The toxin microcystin from Cyanobacteria was associated with diminished CD36 and upregulation of poly ADP ribose polymerase 1 (PARP1) levels in silico, which was confirmed in human lung epithelial carcinoma cells (A427) in vitro and in human adenocarcinoma samples." (PMID 33043031, 2020).
hematological malignancies (9 papers, 2014 to 2024). "There are several ongoing clinical trials on the efficacy of Olaparib, Rucaparib, Niraparib, Veliparib, and, more recently, Talazoparib in overcoming PARP1-mediated resistance in hematological malignancies." (PMID 39200230, 2024). "On the other hand, these findings are reassuring in the increasing warning of treatment-induced hematologic malignancies correlated to PARP1 inhibitor use." (PMID 34944915, 2021). "ABT-888 (Veliparib) is a PARP1/2 inhibitor and is a promising agent in (pre-) clinical development for solid and hematological malignancies especially in combination with DNA damaging agents." (PMID 24833108, 2014). "Although the clinical potential of PARP-1 inhibitors is unquestionable with more than 100 ongoing clinical trials in both solid tumours and hematologic malignancies (clinicaltrials.gov accessed on 11 November 2021), many PARP-1 inhibitors have poor selectivity." (PMID 35158955, 2022). "With regard to hematological malignancies, parthanatos activation has been reported in 50% of AML patients undergoing AraC and anthracycline therapy, while resistant patients show low expression levels of PARP-1, classifying it as a potential biomarker of drug resistance." (PMID 38730609, 2024).
inflammation (8 papers, 2006 to 2025). Aberrant reaction of the microcirculation characterized by movement of fluid and leukocytes from the blood into extravascular tissues. "Protective effects of PARP inhibitors in disease models of acute lung inflammation or septic shock predict a role for PARP-1 in inflammation as well." (PMID 28430591, 2017). "Most of the studies showed the pro-inflammatory effect of PARP-1 in lung inflammation, whereas increased lung inflammation occurred in PARP-1 knockout mice in response to hyperoxia." (PMID 24244594, 2013). "In addition, PARP-1 has a role in several models of inflammation disease, where its absence or inactivation confers protection." (PMID 16356201, 2006). "The present study demonstrates a mechanism to regulate gene expression at the post-transcriptional level, and suggests that blocking the interaction of PARP1 with HuR could be a strategy to treat inflammation-related diseases that involve increased mRNA stability." (PMID 28272405, 2017).
liver (5 papers, 2017 to 2022). "Because of that, previous studies have demonstrated a direct association between PARP-1 expression in different types of gastrointestinal tumors." (PMID 35453444, 2022). "Although most studies have shown that PARP1 inhibitors can effectively enhance the efficacy of chemotherapy drugs, the mutation rate of BRCA1 mutations in most gastrointestinal tumors is actually not high." (PMID 34497808, 2021).
bacterial infection (3 papers, 2014 to 2024). "Herein, we established bacterial infection-induced PARP1-dependent cell death in an AIF-independent manner in mouse monocyte macrophages J774A.1." (PMID 38332126, 2024). "Collectively, our results establish the functional mechanism of YfiD as a potential PARP1 inhibitor and provide more insights into host defense against bacterial infection." (PMID 38332126, 2024). "Inhibition of PARP1 activity impairs the pro-inflammatory response against bacterial infection." (PMID 38332126, 2024). "These inspiring studies hint at the role of PARP1-mediated defense against bacterial infection." (PMID 38332126, 2024). "Moreover, bacterial infection can promote the expression of PARP1 and the activation of inflammation related pathways, and the inhibition of PARP1 has been repeatedly confirmed by experimental models to improve the inflammatory response and increase the survival rate." (PMID 39850582, 2024).
brain disease (3 papers, 2012 to 2022). "Overall, the overexpression of PARP-1 in a multitude of brain diseases and the capacity of PARP-1 inhibitors to penetrate the BBB, places this enzyme as a desirable therapeutic target for brain disorders that share chronic inflammation and/or oxidative stress and a high rate of DNA damage." (PMID 35158955, 2022). "In addition, brain disease-induced ROS production triggers TRPM2 activation, leading to calcium influx from the extracellular space, and finally triggers cell death cascades that include PARP-1/PARG and caspase-dependent cell-death pathways." (PMID 32825703, 2020).
cardiac disease (3 papers, 2019 to 2022). "These years, PARP1 is reported to regulate in cardiac disease serving as substrate protein of many ubiquitin ligases and participating in ubiquitin-proteasome pathway, which broaden the molecular mechanism study of PARP1." (PMID 36257929, 2022). "Future research should elucidate the relevance of the DNA damage-induced PARP1 activation pathway in clinical AF with or without underlying heart diseases." (PMID 30898999, 2019).
hematologic cancer (3 papers, 2019 to 2025). "Exposure of hematologic cancer cell lines and patient-derived cell samples to various HDACi resulted in a significant caspase-independent inhibition of protein PARylation, mainly catalyzed by PARP1." (PMID 36243940, 2022). "We then examined whether ROS/RNS accumulation in APO866-treated hematopoietic tumor cells depends on PARP1 status." (PMID 31803365, 2019).
blood cancer (2 papers, 2019 to 2025). "PARP1 inhibition confers a significant protective effect against APO866-induced cytotoxicity in all of the blood cancer cells that were tested." (PMID 31803365, 2019).
immune disease (2 papers, 2020 to 2022). "We have demonstrated that KYNU and the requirement for tryptophan via WARS, association of the transcriptional activators AHR and HCAR3, along with ADPR and PARP1, are sufficient drivers for persistent immune disease." (PMID 36499104, 2022). "All these data provide evidences that PARP-1 and poly ADP-ribosylation can be important in regulating immunity and underscores the relevance of PARP-1 inhibitor development for immune disorders." (PMID 33053746, 2020).
neurodevelopmental disorder (2 papers, 2022 to 2024). A behavioral and cognitive disorder with onset during the developmental period that involves impaired or aberrant development of intellectual, motor, or social functions. "Pesticides exposure could increase the activity of PARP1 expression, promote the death of nerve cells, affect the signal transduction of neurons, and lead to synaptic and behavioral changes related to neurodevelopmental disorders (NDDs)." (PMID 39020327, 2024).
retinal disorder (2 papers, 2018 to 2024). Any disease or disorder of the retina. "The activation of PARP-1 disrupts mitochondrial membrane function, elevates ROS levels and impairs antioxidant enzymes like manganese superoxide dismutase, contributing to oxidative stress-related retinopathy." (PMID 39458649, 2024). "The combination of poly (ADP-ribose) polymerase-1 (PARP-1) inhibitors with other promising therapeutic agents could provide unique treatment solution against the pathophysiology of several retinal disorders." (PMID 39458649, 2024). "Therefore, through inhibition of PARP-1 activity, retinopathy can be prevented in diabetic individuals." (PMID 29937497, 2018).
benign tumors (1 paper, 2018). "Of these, 15 proteins (PRSS8, MK, WFDC2 (HE4), IL-10, SOD2, PARP-1, hK11, PVRL4, MUC-16 (CA125), FR-alpha, CDH3, NTRK3, IL-8, IL-17C, EN-RAGE) were selected from the comparison between OC stage I–IV and benign tumors." (PMID 30519148, 2018).
CNS tumors (1 paper, 2011). "The pediatric CNS tumors revealed a relatively strong PARP1 protein expression." (PMID 22184287, 2011). "Therefore we investigated whether high PARP1 expression is a biomarker of unfavorable prognosis in high grade pediatric CNS tumors." (PMID 22184287, 2011). "PARP1 protein expression was determined by immunohistochemistry in non-malignant brain tissues and pediatric CNS tumors." (PMID 22184287, 2011).
genetic disease (1 paper, 2021). "Similar results were observed when we employed primary patient fibroblasts from XRCC1-mutated disease, suggesting that increased PARP1 trapping during BER is also a feature of this human genetic disease." (PMID 34102106, 2021).
gynecological tumors (1 paper, 2023). "PARP1 inhibitors (ABT‐888) are also of selective value in other gynecological tumors." (PMID 36525280, 2023).